IL6 (interleukin 6)
Diseases named in the same sentence as IL6 in open-access papers (continued):
Sharing a sentence is not in itself a finding about the gene and the disease.
infection (continued). "In addition, some studies found that the levels of IL‐2, IL‐4, IL‐6, IL‐7, IL‐10, IP‐10, MCP‐1, TNF‐α, MIP‐1α, IFN‐γ, and G‐CSF in patients with severe COVID‐19 infection were significantly higher than those in patients with mild and moderate infection." (PMID 36684101, 2023). "Genetic complementation largely resulted in release of chemokines and cytokines that were not significantly different from their cognate WT infection with the noted exceptions of IL-8, IL-6 and IL-1Ra that did not demonstrate expression levels comparable to WT." (PMID 37669276, 2023). "As IL-6 was maximally up-regulated in Group_1 B (intrauterine death), a potential etiological correlation between intrauterine death and infection may not be excluded." (PMID 37569597, 2023). "Recombinant IL-6 did not increase infection level in activated CD4 + T cells." (PMID 37202790, 2023). "Extensive infection leads to the alteration of early cellular gene expression in activated macrophages, followed by sustained release of pro-inflammatory cytokines and chemokines, including TNF-α, MCP-1, IL-1β, IL-6, IL-8, MIP-1α, and MIP-1β, along with reactive oxygen and nitrogen radicals." (PMID 38035334, 2023). "The direct interaction or infection of eosinophils by RSV may explain their altered immune response as activated eosinophils secrete proinflammatory cytokines like CCL5, IL-6, and MIP-1α after viral interaction resulting in a proinflammatory milieu and increased influx of proinflammatory cells." (PMID 37896776, 2023). "Proinflammatory cytokines, which are produced at the site of infection by activated accessory immune cells, leading to endocrine, autonomic and behavior changes, include interleukin-1α and β (IL-1α and IL-1β), tumor necrosis factor-α (TNF-α) and interleukin-6 (IL-6)." (PMID 37582716, 2023). "Corticosteroids, antivirals, interferons, and monoclonal antibodies directed against immune system proteins, such as interleukin-6 (IL-6), or against certain SARS-CoV-2-specific targets were investigated in order to tackle either the viral replication cycle or the inflammation related to infection." (PMID 36899912, 2023). "At 8 h and 12 h post-infection, the levels of TNF-α, IL-6, and MCP-1 in both primary astrocytes and BV2 cells infected with the two S. parasuis strains were significantly higher than those of cells infected with S. suis strain P1/7, except for the MCP-1 in primary astrocytes at 12 h post-infection." (PMID 37111486, 2023). "The canonical proinflammatory cytokines, including IL-1β/IL-6, did not increase after infection, indicating that hBMECs might not be the primary source of inflammatory cytokines in JEV-induced CNS inflammation." (PMID 37752509, 2023). "While baseline levels of all cytokines were increased among patients who have developed a sternal infection, at discharge only the level of interleukin 6 remained significantly higher compared to no infection groups (92.6 ± 23.6 pg/ml vs. 71.6 ± 12.9 and 79.6 ± 17.7 pg/ml, p < 0.05)." (PMID 37637509, 2023). "Pro-inflammatory (IFNγ, IL-6, TNFα), Treg (IL-10, TGFβ1, TGFβ3), Th9 (IL-9), Th17 (IL-17), and Th2 (IL-4, IL-13) cytokines, total IgM and IgG, as well as gene expressions of FoxP3, STAT5+, IFNγ-R1, and ROR alpha+, were measured at day 1, day 7, day 14, day 21, and day 28 post-infection." (PMID 37569646, 2023). "In contrast, elevation of inflammatory IL-6 and IL-18 was independent of time of infection." (PMID 37490342, 2023). "The level of IL-6 in healthy people is very low, generally not more than 7 pg/ml, while the level of IL-6 in serum of septic patients increases rapidly in the early stage of infection, and can reach the peak within 2 h." (PMID 38027268, 2023). "Further, in those clinically diagnosed with a postnatal infection in the absence of antenatal infection concerns, IL-6 increases before CRP, emphasizing a potential role for expanded biomarker screening if antibiotics are initially avoided in infants delivered for maternal indications." (PMID 37606448, 2023).
infection (continued). "RT-qPCR did not reveal significant differences in the amount of TMEV RNA as well as Ifnb1, Isg15, Eif2ak1 (PKR), Tnfa, Il1a, Il1b, Il6, Il10, Il12 (p40) and Ifng transcript numbers in the brain of Asc−/− and Casp1−/− mice and their respective wild type littermates at 4 days after TMEV infection." (PMID 37414913, 2023). "Although infection did not influence mRNA expression level of Ifn-β gene inside macrophages cultured on titanium surfaces and titanium with silver or tetracycline, the expression levels of Tnf-α, Cxcl-1 and Il-6 genes significantly increased." (PMID 37929187, 2023). "The infection of MDMs with Mtb opsonized with hSAA-1, compared to the infection with nonopsonized bacilli, led to at least a 2-fold increase in the concentrations of CSF2, CSF3, IL-1α, IL-1β, IL-6, IL-12, CCL15, and TNF-α with the most potent 10-fold increase observed for CCL5." (PMID 37781389, 2023). "Our results agreed with this because they showed inhibition of TNF-α and IL-6 production and the absence of stimulation of cytokines that are important in CL control, suggesting that other mechanisms are necessary to control the infection." (PMID 37255095, 2023). "This shows that IL-6, while being a valuable early infection marker, does not offer definitive prediction regarding the intensity of infection in newborns—whether it constitutes a moderate infection or EOS." (PMID 38255366, 2023). "Moreover, mice subjected to LEM-EO and COR-EO prophylaxis displayed lower colonic numbers of macrophages/monocytes and of T lymphocytes, respectively, whereas in both verum groups, basal IL-6 and IFN-γ concentrations were measured in mesenteric lymph nodes on day 6 post-infection." (PMID 37065112, 2023). "Interestingly, no reversal of the infection phenotype of the IL-6 transgenic parasites was observed upon IL-6R blockade." (PMID 37143657, 2023). "In addition, the concentrations of IL-6 and various immunoglobulins (IgG, IgM, IgD, IgE, IgA, and IgG3) were determined in the serum of patients diagnosed with postoperative infections and compared to those of patients who had no signs of infection." (PMID 37189842, 2023). "Moreover, the pDC-dependent increase in IL-6 and TNF levels was observed only when pDCs were in direct contact with MDMs, further supporting an additive/promotive role of pDCs in this cellular response to infection." (PMID 37253946, 2023). "Notably, however, SARS-CoV-2 evoked both IFN-β and IL-6 expression at a later stage of infection regardless of culture temperature and correlated with the induction of RIG-I which was observed only in SARS-CoV-2-infected cells." (PMID 36507221, 2023). "Cytokines (IL-1β, IL-6, IL-8, TNF-α, IFN-β, IFN-γ, etc.), mainly derived from mononuclear phagocytes and other antigen-presenting cells, play important roles in defending against pathogen infection and in promoting infiltration of inflammatory cells in tissues." (PMID 38053560, 2023). "This is because IL-6 blockade may interfere with the beneficial eATP metabolism accomplished by CD39 upregulation, which plays a crucial role in managing the immune response during infection." (PMID 37818368, 2023). "Unlike IFN-β, the level of produced IL-6 markedly increased up to 400 pm/ml in miR-141 transduced cells at 24 h post-infection, while significantly decreased in cells transfected with the inhibitor antagonist miR-141, indicating the role of miR-141 in IL-6 signaling pathway in infected cells." (PMID 37596622, 2023). "Cytokines, including interleukin-6 (IL-6), interferon-inducible protein-10 (IP-10), and macrophage inflammatory protein 1 (MCP-1), were substantially elevated in blood and were correlated with activated CD4+ T cells, B cells, CD16+CD56+ NK cells, CD14+CD16+ monocytes during infection." (PMID 37033979, 2023). "However, CATH-1 significantly increased the secretion of IL-1β and IL-6 while it did not change the secretion of TNF-α when CATH-1 was incubated with cells at post-infection." (PMID 37605242, 2023).
infection (continued). "Interestingly, classic IL6 signaling seems to be of profound importance for the organisms’ control of infection, whereas restricting IL6 trans-signaling did not restrain this ability." (PMID 36151360, 2023). "For BeWo cells, our results showed that in the absence of infection, concentrations of 32 μg/mL of the hydroalcoholic extract and oleoresin induced an increase in IL-6 levels in comparison to untreated cells (medium) (*P < 0.05, **P < 0.001) and SDZ + PYR (&P < 0.05)." (PMID 36860986, 2023). "Cytokine signaling of IL-1β, IL-23, IL-17A, CCL7, CXCL10, TRAIL, CD40L, and BAFF provides protection against acute WNV infection in mice; IL-10 and IL-22 aid in WNV pathogenicity; IL-6 and IL-12 had no apparent effect during infection; and CCL2, TNF-α, and FasL roles remain elusive." (PMID 36992514, 2023). "Still, we did not observe any increased infection by those cytokines, aside from IL-6." (PMID 37202790, 2023). "Additionally, we found that cytokines were significantly related to the occurrence of sternal infection initially, with interleukin 6 levels remaining significantly higher in patients with sternal infection compared to those without infection." (PMID 37637509, 2023). "In addition, Li and Zhang found that miR-708-5p influenced M. tuberculosis viability and the human macrophage inflammatory response during infection by targeting TLR4 and miR-708-5p mimics reduced proinflammatory factors including IFN-γ, interleukin-6 (IL-6), IL-1β, and TNF-α." (PMID 36912627, 2023). "The disruption of the epithelial barrier due to intestinal dysbiosis, infection, and injury results in the entry of bacteria and their metabolites into the bloodstream, which can promote systemic inflammation characterized by elevated plasma TNF-α, IL-6, and IL-1β levels." (PMID 36675302, 2023). "Subsequent infection experiments with 107 CFU wild-type AC047 and AC047ΔsctV showed that a lack of T3SS results in slower bacterial clearance from the lungs and significantly lower inflammatory responses in comparison with wildtype, as seen by reduced IL-6 and keratinocyte chemoattractant levels." (PMID 37598340, 2023). "In this animal strain and using this protocol, we could test the effects of Ac2-26 following infection with other DENV serotypes and observed a significant reduction in haematological alterations, liver damage, and IL-6 production induced by either DENV-1, DENV-3, or DENV-4." (PMID 35293862, 2022). "Some studies suggested that system or local infection could increase release of thrombopoietin and different inflammatory cytokines, such as IL-1, IL3 and IL6 and tumor necrosis factor-α, result in increasing thrombopoiesis and lead to the production of younger large platelets in blood circulation." (PMID 35614411, 2022). "IL-6 KO mice had no survival advantage over WT animals and only a single mouse survived infection." (PMID 35587473, 2022). "However, de novo infection of HUVECs with ΔKapB BAC16 did not cause PB disassembly, and steady-state levels of IL-6 RNA, an ARE-containing cytokine transcript known to be regulated by PB levels, were reduced relative to that after WT infection." (PMID 34936820, 2022). "Second, the current review did not include more factors affecting post-PCNL infection, such as IL-6, PCT, CRP, stone load, amount of hemoglobin drop, size of the puncture channel, amount of bleeding, amount of intraoperative lavage, and renal perfusion pressure." (PMID 36515726, 2022). "The present study, revealed the significant up-regulation of pro-inflammatory cytokines, such as, IL-1β, IL-6, IL-10, IFN-γ and non-significant elevation of TNF in infected controls on the 9th day post-infection, showing an association with disease severity that supports previous findings." (PMID 36510199, 2022).
infection (continued). "Nevertheless, the cDC2 subset was recruited at higher numbers to ICAM-1/2-/- LNs following PR8 infection, and were hyperactivated, as evident by their significantly elevated levels of the major co-stimulatory molecules CD80 and CD86, as well as elevated IL-6 production." (PMID 36895258, 2022). "However, MIA has been associated with an increase in cytokine synthesis and release, including IL-6 and IFN-γ among others (e.g., IL-1β, TNF-α) in response to infection and external factors during pregnancy both clinically and in experimental in vivo models of MIA." (PMID 36300375, 2022). "CRP, PCT or IL-6 alone could not be used to determine whether the patients with culture-negative BALF had infection." (PMID 36237436, 2022). "Therefore, the question of whether combined treatment with alloferon and zanamivir can suppress production of IL-6 and MIP-1α after infection with H1N1 was examined." (PMID 36614125, 2022). "For patients with a history of COVID-19 infection, vaccination may further increase both inflammatory and immunostimulatory cytokines, including IL-6, compared to patients who have not had the infection." (PMID 35746474, 2022). "While infection with either virus triggered robust transcriptional interferon responses, including induction of type I (IFNB1) and type III (IFNL1) interferons, markedly lower levels of interferons and inflammatory proteins (IL-6, IL-8) were released following SARS-CoV-2 compared to H1N1 infection." (PMID 35840680, 2022). "The IL-6 concentration did not change over the course of the infection (not shown)." (PMID 36146875, 2022). "In comparison to other biomarkers like CRP and IL-6, which have inadequate sensitivities at different stages of an illness, SAA was found to be a reliable screening sign for the first 24 hours following infection start, thus raising its potential relevance as a biomarker." (PMID 35449688, 2022). "Despite the increased number of neutrophils in the lung, we failed to observe a rise in the expression of the pro-inflammatory cytokines, TNFα, IL1β or IL-6, in the lung of aged mice after infection, when compared to the lungs of young-infected mice (data not shown)." (PMID 35392033, 2022). "Therefore, we measured the secretion of pro-inflammatory (IL-8, IL-12a, IL-15, IL-6) cytokines by qPCR at different times after HKDM infection with WT and ∆EseN mutant, and uninfected HKDM as a negative control." (PMID 35889053, 2022). "Significantly higher levels of IL-6 were seen in cells infected by clinical isolates B12 (846 pg ul−1) and D1 (998 pg ul−1) when compared to the cells infected by PAO1 (530 pg ul−1) and PA14 lab strains (334 pg ul−1) at 24 h post-infection (One-way ANOVA, Tukey post-hoc, P<0.05)." (PMID 35275806, 2022). "A total of 149 patients with infection and 215 without infection were tested for IL-6." (PMID 35453256, 2022). "IL6 is an early biomarker for inflammatory complications such as infection or acute rejection and might, therefore, not be a suitable candidate for predicting long-term complications." (PMID 35887906, 2022). "Also similar to our results with macrophage cell lines, Δ51-infected WT primary BMDM secreted increased interleukin 6 (IL-6) and IL-1β and accumulated ROS, unlike in WT or Δ51C infection." (PMID 35467412, 2022). "However, numerous studies have shown that several pro inflammatory cytokines, including IL-6 and TNFα increase with age in healthy individuals and in the absence of infection." (PMID 35700185, 2022). "(2018) demonstrated that PD-L1 expression, along with PD-L2, IL-10, IL-6, and Macrophage-Inflammatory-Protein-1- alfa (MIP-1-α), was up-regulate on Dermal Dendritic Cells (DDCs) and in immature monocyte-derived DCs (moDCs) after infection by S. mansoni cercariae." (PMID 36148227, 2022).
infection (continued). "Groups of A129 IFNAR−/− mice were infected with 105 FFU of wt SFTSV, and administered either an anti-IL-6 antibody (2B Scientific; BE0046) or an isotype control antibody (BioXCell; BP0089) at PID −2 (prophylactic, before infection) or at PID 2 (therapeutic, after infection)." (PMID 35529317, 2022). "At this stage of research, however, it cannot be conclusively stated whether FRSMb can entirely replace pro- and prebiotics, organic acids, and enzyme additives in the diet of piglets, in part because the increase in the levels of IL-6 and of LOOH and MDA may be indicative of infection." (PMID 36130989, 2022). "Among the hypotheses, it is thought that, as for the olfactory mucosa, the expression of ACE-2 receptors in the oral mucosa, ascertained in the taste buds, can favor the infection and therefore induce a “cytokine storm” due to TNF-α, IL-6, and IFN-γ overexpression." (PMID 35269410, 2022). "Macrophages which lacked IL-6 were killed early in infection." (PMID 35297653, 2022). "In addition, COPD cultures demonstrated up-regulated basolateral secretion of IL-6, IL-8, GM-CSF, and eotaxin 3, regardless of infection." (PMID 35280870, 2022). "The AAV9-SLPI infection has significantly reduced inflammatory cytokine levels when compared with AAV9 group (TNF-α: 85.92 ± 36.24 ng/mg vs. 186.1 ± 12.17 ng/mg, p < 0.05, IL-1β: 29.48 ± 4.20 ng/mg vs. 69.03 ± 9.17 ng/mg, p < 0.05, and IL-6: 74.23 ± 10.50 ng/mg vs. 113.1 ± 28.43 ng/mg, p < 0.05)." (PMID 36061560, 2022). "In glial cells, Tha and Th2P-4M infection did not induce significant expression of the selected proteins, although modest modulations of constitutively expressed proteins (IL-1β, IL-6, LIF) that were detected in astrocytic cells and/or in microglia-like HMC3 were recorded." (PMID 36680128, 2022). "However, when acetate was included in the Hi2019WT infection assay, an anti-inflammatory effect was observed that resulted in a 47% (2-Way ANOVA, p = 0.0021) and 26% (2-Way ANOVA, p = 0.0001) reduction of IL-6 and IL-8 expression, while IL-1β expression was essentially unchanged." (PMID 35085362, 2022). "Patients with infection had a significantly higher frequency of fever (77.8% vs. 51.5%, p = 0.011) and IL-6 levels (1450 ± 791 vs. 674 ± 149 pg/mL, p = 0.007) at admission than those without infection, but significantly lower serum creatinine levels (0.9 ± 0.5 vs. 1.5 ± 1.1, p = 0.031)." (PMID 36555941, 2022). "In this study, IL-6 levels were shown to be considerably greater in non-infected NHL cases than in healthy individuals, while IL-6 levels were significantly higher in infected NHL patients and linked with infection severity." (PMID 35463642, 2022). "Previous studies in a fish model of infection with A. hydrophila demonstrated the expression of RELA gene and the NF-κB pathway that could result in the production of several cytokines such as TNF-α, IL-1β, IL-12, IL-8, IL-6, and IFN." (PMID 35874671, 2022). "Tumor necrosis factor-α (TNF-α), interleukin-6 (IL-6) and interferon-γ (IFN-γ) are the most important cytokines involved in inflammation and could induce an innate immune system to manage the infection." (PMID 35606770, 2022). "Furthermore, it moderately increased the expressions of proinflammatory cytokines including IL-1β, IL-6, and TNF-α in the early stage of infection and decreased their release rapidly in the later stage, while regulated the same phase change of anti-inflammatory cytokine IL-10." (PMID 35071595, 2022). "Since 20% of participants in both cohorts report resolution of PASC between 4 and 12 weeks after infection, we asked whether there are trends toward normalization of IL-1β, IL-6, and TNF levels with elapsed time after infection in individuals reporting ongoing symptoms." (PMID 35732153, 2022).